KRAS (KRas proto-oncogene, GTPase)
Diseases named in the same sentence as KRAS in open-access papers (continued):
Sharing a sentence is not in itself a finding about the gene and the disease.
leukocytosis (5 papers, 2020 to 2025). "Following in vivo screening of three asTF-proficient human PDAC cell lines, we chose to make use of KRAS G12V-mutant human PDAC cell line PaCa-44, which yields aggressive primary orthotopic tumors with spontaneous spread to PDAC-relevant anatomical sites, along with concomitant severe leukocytosis." (PMID 38473827, 2024).
malignant glioma (5 papers, 2015 to 2024). A grade III or grade IV glioma arising from the central nervous system. "Furthermore, the oncogenic version of KRAS protein, KRAS G12X, which is associated with aggressive disease in human cancer including malignant glioma, was shown to promote initiation and rapid tumour progression in a zebrafish model of human malignant glioma." (PMID 29113296, 2017). "The combined features of diverse tumor cell morphology, high cellularity, presence of mitotic figures and regional necrosis indicate that the onogenic KRAS-induced tumors are most likely malignant gliomas." (PMID 25644510, 2015).
non-small cell lung adenocarcinoma (5 papers, 2018 to 2024). Type of epithelial lung cancer arising from glandular origin. "This study aimed to investigate the incidence of KRAS mutations, and concomitant mutations, in advanced non-small cell lung adenocarcinoma patients." (PMID 34684076, 2021). "Its therapeutic effects on non-small cell lung adenocarcinoma carrying KRAS mutation and their immune system are less understood." (PMID 29844447, 2018).
papillary adenocarcinoma (5 papers, 2009 to 2023). A morphologic variant of adenocarcinoma. "In one of the predominant papillary adenocarcinomas, the papillary and micropapillary subtypes were KRAS wild type, but a KRAS mutation was present in the solid with mucin subtype." (PMID 24742923, 2014).
plasmacytoma (5 papers, 2006 to 2025). Plasmacytoma is a localized mass of neoplastic monoclonal plasma cells that represents approximately 5% of all plasma cell neoplasms. "KRAS gene mutation was detected in seven patients (in six bone marrow samples and one plasmacytoma sample), and NRAS gene mutation was detected in six patients (in five bone marrow samples and one plasmacytoma sample)." (PMID 36833278, 2023). "The frequency of the KRAS, NRAS, and BRAF gene mutations in any of the tumor substrate (bone marrow, ctDNA, plasmacytoma) in the entire group was 50% (56 out of 113)." (PMID 40943426, 2025). "We have measured KRAS, NRAS, and BRAF gene mutations in circulating free tumor DNA (ctDNA) from plasma, bone marrow, and plasmacytoma samples as well as their correlation with various clinical and laboratory parameters." (PMID 40943426, 2025). "Mutations in the KRAS, NRAS, and BRAF genes either in bone marrow, ctDNA, or plasmacytoma samples were found in 50% of patients." (PMID 40943426, 2025). "Here, we present an analysis of the STR profiles and mutation status of the KRAS, NRAS, and BRAF genes, evaluated in plasma free circulating tumor DNA (ctDNA), CD138+ bone marrow cells, and plasmacytomas." (PMID 39273371, 2024). "The mutation status of the KRAS, KRAS, and BRAF genes in ctDNA, CD138+ bone marrow cells, and plasmacytomas was analyzed by AS-PCR and NGS." (PMID 39273371, 2024). "Notably, all these rare KRAS and NRAS gene mutations were found only in the group of patients with plasmacytoma." (PMID 40943426, 2025). "In the 11 extramedullary plasmacytomas, mutations were detected in the NRAS gene in 27% of cases (n = 3) and in the BRAF gene in 18% (n = 2), suggesting a tendency for KRAS mutations to be more frequent in bone lesions, while NRAS mutations were more common in extramedullary sites." (PMID 40943426, 2025). "In two patients, there was a mutation in the KRAS or NRAS gene in plasmacytoma tissue, while the corresponding gene was not mutated in bone marrow or ctDNA." (PMID 39273371, 2024). "NRAS or KRAS genes were mutated in plasmacytomas, while in the bone marrow or plasma ctDNA the genes were not affected." (PMID 36833278, 2023). "A principal finding of this work is that mutations in KRAS, NRAS, or BRAF genes within ctDNA were significantly more prevalent in patients with plasmacytoma compared to those without (28% vs. 0, p = 0.0007)." (PMID 40943426, 2025). "The presence of mutations in the KRAS, NRAS, and BRAF genes is more prevalent in the ctDNA of patients with plasmacytoma compared to those without." (PMID 40943426, 2025).
pyloric gland adenoma (5 papers, 2012 to 2026). A rare neoplastic polyp that arises from the stomach. "GNAS and KRAS mutations are frequently observed in pyloric gland adenomas and gastric‐type adenocarcinomas and are considered to represent characteristic molecular alterations in G‐type NADETs." (PMID 40964650, 2026). "KRAS codon 12 mutations have been previously reported in two cases of pyloric gland adenoma of the main pancreatic duct, and probably support the neoplastic nature of this tumour." (PMID 23206236, 2012). "Sequencing analysis of KRAS exon 1 and 2 showed a point mutation at exon 1, codon 12 (c.35G>T; p.G12V) and wildtype sequence at exon 2 in the pyloric gland adenoma and the same mutation in the adjacent BilIN-3." (PMID 23206236, 2012). "Additionally, GNAS and KRAS mutations have been frequently observed in pyloric gland adenoma, IPMNs, and pancreatic intraepithelial neoplasia, respectively." (PMID 37371022, 2023). "Also in the present case, the pyloric gland adenoma and the BilIN-3 harbored a KRAS codon 12 mutation, indicating a possible metaplasia-dysplasia-carcinoma sequence with a common tumourigenesis." (PMID 23206236, 2012). "Similarly, frequent concurrent presence of KRAS and GNAS mutations was also detected in colorectal villous adenomas and pyloric gland adenomas." (PMID 24312577, 2013). "Indeed, molecular changes reported in pyloric gland adenomas, such as GNAS and KRAS gene alterations, were also found in areas of gastric heterotopia of the duodenum." (PMID 33922305, 2021).
sarcopenia (5 papers, 2022 to 2025). Progressive decline in muscle mass due to aging which results in decreased functional capacity of muscles. "Higher SII levels are associated with higher TNM stages, higher tumor grades, sarcopenia, KRAS mutations, lymphovascular invasion, older age, and right-sided CRC." (PMID 40843730, 2025). "DA-Raf exerts tumor-suppressing and invasion-suppressing functions to cancer cells with oncogenic KRAS mutations, DA-Raf also induces skeletal myocyte differentiation and counteracts skeletal muscle atrophy and sarcopenia caused by TGF-β superfamily protein-induced non-Smad Ras–ERK pathway." (PMID 41120211, 2025).
sigmoid colon cancer (5 papers, 2019 to 2025). A malignant neoplasm involving the sigmoid colon. "In patients with colon or sigmoid colon cancer, the SUVmax had a greater accuracy in predicting KRAS mutations, whereas in patients with rectal cancer, the accuracy of the SUVmax in predicting KRAS mutations was the same as that of TW40." (PMID 40909964, 2025).
signet ring cell carcinoma (5 papers, 2016 to 2023). A usually aggressive, poorly differentiated invasive adenocarcinoma characterized by the presence of malignant glandular cells in which the nucleus is pressed to one side by the presence of intracytoplasmic mucus. "The histological subtype and clinical-stage features were also excluded due to insufficiently large subcategories such as signet ring carcinoma histological type and clinical stage 2 having less than ten cases for KRAS mutants and wildtypes." (PMID 32628708, 2020). "For example, the IDH1 mutations we detected by NGS in Idylla-detectable BRAF or KRAS mutation positive CRC specimens are associated with mucinous or signet ring cell adenocarcinoma, thus providing molecular support for the correct diagnosis that would not be possible from the Idylla results." (PMID 35627184, 2022).
small cell carcinoma (5 papers, 2016 to 2023). A neuroendocrine carcinoma composed of small malignant cells which are often said to resemble "oat cells" under the microscope. "We identified 265 treatment-naïve patients with non-small-cell carcinoma, who had EGFR mutations (n = 159), KRAS mutations (n = 55), or ALK rearrangements (n = 51)." (PMID 27518729, 2016).
teratoma (5 papers, 2012 to 2025). A non-seminomatous germ cell tumor characterized by the presence of various tissues which correspond to the different germinal layers (endoderm, mesoderm, and ectoderm). "As far as we know, these two cases are unique because currently there have been few report on teratoma-associated adenocarcinoma carrying KRAS oncogene mutation." (PMID 25297496, 2014). "The present report therefore describes for the first time a KRAS codon 12 mutation in a case of PTC with a follicular growth pattern arising in SO in combination with bilateral teratoma." (PMID 22682753, 2012). "In the literature, molecular data show that KRAS and GNAS co-mutations are also present in primitive ovarian PMP associated with teratoma." (PMID 34930348, 2021). "We examined a total of 51 germinomas and 1 mixed GCT (germinoma and teratoma component) for mutations in KIT exons 11, 13, 17 and 18 as well as mutation hotspots in HRAS, KRAS, NRAS and RRAS-2." (PMID 27391150, 2016). "Moreover, the absence of KRAS mutation in the mature teratoma element in our samples suggests that this mutation accompanies with the intestinal-type epithelium." (PMID 25297496, 2014).
testicular cancer (5 papers, 2019 to 2025). A primary or metastatic malignant neoplasm that affects the testis. "Our results confirm the key role of KRAS-targeting somatic mutations, which are well modeled by gene expression in KRAS-driven tumors: colon, lung, pancreas, stomach, and testicular cancers, as well as cervical squamous carcinoma." (PMID 31379928, 2019). "Recent research indicates that KRAS copy number gain is highly prevalent in testicular cancer cells." (PMID 39382942, 2024). "In a previous analysis of molecular alterations of testicular cancer tumors in The Cancer Genome Atlas (TCGA), the authors identified that somatic mutations of three genes—KIT, KRAS, and NRAS—were commonly observed in testicular cancers." (PMID 34819066, 2021).
tubular adenocarcinoma (5 papers, 2013 to 2024). An infiltrating adenocarcinoma in which the malignant cells form tubular structures. "KRAS mutations were also more prevalent in mucinous than tubular adenocarcinomas (61.6% vs. 44.0%, respectively; P = 0.002)." (PMID 26691448, 2015). "One of the two KRAS-mutated tubular carcinomas harbored CDKN2A/p16 mutations." (PMID 28145465, 2017). "The KRAS wildtype tubular carcinoma and one KRAS-mutated tubular carcinoma also lacked alterations in the three other genes, a result that was confirmed by additional extended gene analysis." (PMID 28145465, 2017).
vascular tumor (5 papers, 2021 to 2025). "Vascular tumor thrombus was additionally found in two of four LAMPC patients with KRAS mutations, but not in patients with wild-type KRAS, suggesting that LAMPC patients with KRAS mutations are more likely to develop vascular tumor thrombus (p = 0.0129)." (PMID 36457500, 2022).
villous adenoma (5 papers, 2016 to 2025). An epithelial neoplasm morphologically characterized by the presence of a villous architectural pattern. "While the overall mutational profiles are similar, villous adenomas presented the highest level of KRAS mutations (76.9%)." (PMID 33087131, 2020). "Interestingly, it seems that villous adenomas had a higher KRAS mutation rate than carcinomas, although this was not statistically significant due to the limited sample size." (PMID 39021676, 2024).
acute leukemia (4 papers, 2015 to 2025). A clonal (malignant) hematopoietic disorder with an acute onset, affecting the bone marrow and the peripheral blood. "Of particular interest, NRAS and KRAS mutations were acquired in those patients who progressed to secondary acute leukemia or accelerated phase (MPN02, MPN04, and MPN18)." (PMID 31911629, 2020). "The pediatric group with the largest number of KRASm cases was acute leukemia where diverse KRASm were represented with KRAS G13D and G12D being the most common." (PMID 36494601, 2022).
acute promyelocytic leukemia (4 papers, 2017 to 2022). An aggressive form of acute myeloid leukemia (AML), characterized by arrest of leukocyte differentiation at the promyelocyte stage, due to a specific chromosomal translocation t(15;17) in myeloid cells. "MiR-217 enhances chemosensitivity of AML cells to doxorubicin by targeting KRAS, while miR-204 potentiates the sensitivity of acute promyelocytic leukemia (APL) cells to arsenic trioxide (ATO)." (PMID 35628648, 2022). "Both KRAS and NRAS expressions were not correlated with CR rate among non-acute promyelocytic leukemia (APL) patients [43% (34/79, KASlow) vs 29% (10/34, KRASlow), P=0.210 and 41% (32/79, NRASlow) vs 35% (12/34, NRAShigh), P=0.677]." (PMID 29029494, 2017).
adenocarcinoma in situ (4 papers, 2014 to 2025). A lesion in which the normally situated glands are partially or completely replaced by atypical cells with malignant characteristics. "This is difficult to reconcile with the observation that atypical adenomatous hyperplasia (AAH), the presumed dysplastic precursor of adenocarcinoma, has a higher incidence of KRAS mutation than adenocarcinoma-in-situ and much higher than invasive adenocarcinoma." (PMID 24742923, 2014).
adenosquamous lung carcinoma (4 papers, 2014 to 2017). An aggressive carcinoma with a poor prognosis characterized by a presence of both malignant squamous cells and glandular cells. "In summary, according to the present case and reported literature, lung adenosquamous cell carcinoma with KRAS mutations has high susceptibility to distant metastasis including peritoneal metastasis and a very rapid progression of clinical course." (PMID 28950878, 2017). "Our patient represented a rare case of lung adenosquamous cell carcinoma harboring the KRAS G12A mutation, which metastasized distantly to the peritoneum only, and progressed rapidly." (PMID 28950878, 2017). "In this study, we report an uncommon case of a patient with lung adenosquamous cell carcinoma harboring KRAS G12A mutation with the peritoneum as the sole distant metastatic site." (PMID 28950878, 2017). "In another study of KRAS and EGFR mutations in adenosquamous lung carcinoma, one out of three tumors had an EGFR mutation detected only in the glandular (adeno) component and not in the squamous component." (PMID 24742923, 2014).
appendiceal adenocarcinoma (4 papers, 2013 to 2025). "Volcano plots for four additional tumor types (Sq NSCLC, SBA, ICC, and appendix adenocarcinoma) also support mutual exclusivity of KRAS with other driver alterations." (PMID 36494601, 2022).
atherosclerosis (4 papers, 2022 to 2025). A disease characterized by the build-up of fatty material and calcium deposition in the arterial wall resulting in partial or complete occlusion of the arterial lumen. "KRAS can induce smooth muscleproliferation and migration, participating in the process of atherosclerosis." (PMID 41259792, 2025). "miR‐152‐3p has been shown to aggravate vascular endothelial dysfunction under hypoxia, and bioinformatics analysis suggests it regulates KRAS to contribute to atherosclerosis pathogenesis." (PMID 40391195, 2025). "A protooncogene—KRAS (Kirsten rat sarcoma virus)—was found to be a target of miR-126-3p, miR-200c-3p, and miR-155-5p, confirming emerging evidence of its critical role in atherosclerosis and ischemic stroke." (PMID 39337512, 2024).
Autoimmunity (4 papers, 2017 to 2024). The occurrence of an immune reaction against the organism's own cells or tissues. "Somatic mutation in NRAS or KRAS may cause a rare autoimmune disorder coupled with abnormal expansion of lymphocytes." (PMID 28736556, 2017). "All PRKCD, CTLA4, TET2 and NRAS/KRAS patients presented clinically with lymphoproliferation and autoimmunity, considering all those reported cases (n=197) as ALPS-like patients." (PMID 34447369, 2021). "However, only 100% of CTLA4, PRKCD, TET2 and NRAS/KRAS reported patients had an ALPS-like presentation, while the autoimmunity and lymphoproliferation combination resulted rare in other genetic defects." (PMID 34447369, 2021).
bladder urothelial carcinoma (4 papers, 2020 to 2025). "As suggested by the responsiveness of the patient’s cells to MEK inhibitor trametinib, the tumor cells were found to harbor a somatic activating KRASG12V mutation reflecting results from earlier studies reporting KRAS mutations being more common in UrAC than in urothelial bladder cancers." (PMID 32576176, 2020).
bone tumors (4 papers, 2018 to 2025). "The recent expansion of the range of druggable KRAS alleles has opened new clinical opportunities to treat rare KRAS-mutant bone cancers." (PMID 40779492, 2025). "Bone cancers have not been traditionally well represented in KRAS inhibitor clinical trials because of the low frequency of KRAS mutations and the infrequency of G12C." (PMID 40779492, 2025). "The analysis of IHC staining showed that upregulating MAZ enhanced, while silencing MAZ repressed HRAS and KRAS expression in the bone tumor tissues from tibia in different mice groups, confirming the positive correlation of MAZ with HRAS and KRAS in these PCa cells." (PMID 31488180, 2019).
bronchioalveolar carcinoma (4 papers, 2012 to 2020). "Many studies have shown that KRAS mutation is more common in mucinous than nonmucinous bronchioalveolar carcinomas, especially in smokers." (PMID 23119210, 2012).